CACNA1G (calcium voltage-gated channel subunit alpha1 G)
Description:
Voltage-sensitive calcium channels (VSCC) mediate the entry of calcium ions into excitable cells and are also involved in a variety of calcium-dependent processes, including muscle contraction, hormone or neurotransmitter release, gene expression, cell motility, cell division and cell death. The isoform alpha-1G gives rise to T-type calcium currents. T-type calcium channels belong to the 'low-voltage activated (LVA)' group and are strongly blocked by mibefradil. A particularity of this type of channel is an opening at quite negative potentials and a voltage-dependent inactivation. T-type channels serve pacemaking functions in both central neurons and cardiac nodal cells and support calcium signaling in secretory cells and vascular smooth muscle. They may also be involved in the modulation of firing patterns of neurons which is important for information processing as well as in cell growth processes. [Isoform 2]: Voltage-sensitive calcium channels (VSCC) mediate the entry of calcium ions into excitable cells and are also involved in a variety of calcium-dependent processes, including muscle contraction, hormone or neurotransmitter release, gene expression, cell motility, cell division and cell death. The isoform alpha-1G gives rise to T-type calcium currents.
Synonyms: Cav3.1; NBR13; Ca(V)T.1; SCA42; SCA42ND
Tractability: Small molecule: an approved drug acts on it; a structure with a bound ligand is known; a high-quality ligand is known; it belongs to a druggable protein family. Antibody: UniProt places it where antibodies can reach, with high confidence; its Gene Ontology location is reachable by antibodies, with high confidence; UniProt predicts a signal peptide or a membrane-spanning region. PROTAC: a small molecule that binds it is known.
Target class: Voltage-gated calcium channel; Ion channel; Voltage-gated ion channel
Chemical probes: CHEMBL3115194
Gene: Protein-coding gene on chromosome 17 (50,560,715 to 50,627,474, forward strand). Ensembl gene ENSG00000006283.
Subcellular location: Cell membrane; Cytoplasm
Subcellular location (Human Protein Atlas): Acrosome; Equatorial segment; Nucleoplasm; Perinuclear theca; Cytosol; Nuclear bodies
Pathways (Reactome):
Developmental Biology: NCAM1 interactions
Muscle contraction: Smooth Muscle Contraction
Gene Ontology:
Molecular function: low voltage-gated calcium channel activity; scaffold protein binding; voltage-gated calcium channel activity; high voltage-gated calcium channel activity; voltage-gated calcium channel activity involved in AV node cell action potential; voltage-gated calcium channel activity involved SA node cell action potential; monoatomic ion channel activity
Biological process: calcium ion import; calcium ion transmembrane transport; regulation of membrane potential; AV node cell action potential; AV node cell to bundle of His cell signaling; calcium ion import across plasma membrane; cardiac muscle cell action potential involved in contraction; membrane depolarization during AV node cell action potential; membrane depolarization during SA node cell action potential; regulation of heart rate by cardiac conduction; SA node cell action potential; SA node cell to atrial cardiac muscle cell signaling; sinoatrial node development; monoatomic ion transport; transmembrane transport
Cellular component: cytoplasm; plasma membrane; voltage-gated calcium channel complex; membrane
Genetic constraint (gnomAD): Loss-of-function variants: 65 observed, 196.84 expected, observed/expected ratio (o/e) 0.33, 90% interval 0.27 to 0.41. The upper end of that interval is the gene's LOEUF score, 0.41, which puts it in group 1 of 6, group 1 being the genes least tolerant of losing a copy. Missense variants: 2,370 observed, 3,145.6 expected, observed/expected ratio (o/e) 0.75, 90% interval 0.73 to 0.78. Synonymous variants: 1,285 observed, 1,297.8 expected, observed/expected ratio (o/e) 0.99, 90% interval 0.94 to 1.04.
Gene-disease validity (ClinGen):
ClinGen rates the evidence that CACNA1G causes each of these diseases.
spinocerebellar ataxia type 42 (autosomal dominant): Definitive.
Homologues: Orthologues: chimpanzee CACNA1G (99% identical), macaque CACNA1G (99% identical), pig CACNA1G (95% identical), mouse Cacna1g (95% identical), rat Cacna1g (94% identical), guinea pig CACNA1G (94% identical), dog CACNA1G (92% identical), rabbit CACNA1G (91% identical), tropical clawed frog cacna1g (64% identical), zebrafish cacna1g (59% identical). Paralogues in human: CACNA1H (54% identical), CACNA1I (47% identical), CACNA1B (22% identical), CACNA1A (21% identical), CACNA1E (21% identical), CACNA1D (20% identical), CACNA1C (20% identical), CACNA1F (20% identical), CACNA1S (20% identical), SCN1A (19% identical), SCN2A (19% identical), SCN3A (19% identical), and 14 more.
Diseases named in the same sentence as CACNA1G in open-access papers:
CACNA1G is named in the same sentence as 120 diseases in open-access papers, as found by Europe PMC text mining. Sharing a sentence is not in itself a finding about the gene and the disease. The quoted sentences say what the papers report.
epilepsy (22 papers, 2008 to 2025). A brain disorder characterized by episodes of abnormally increased neuronal discharge resulting in transient episodes of sensory or motor neurological dysfunction, or psychic dysfunction. "Cav3.1 was previously identified as a genetic modifier of epilepsy in Scn1a+/− mice, as genetic knockdown of the Cav3.1-encoding gene Cacna1g was reported to ameliorate spontaneous seizures and improve survival." (PMID 37082241, 2023). "Damaging variants in CACNA1G leads to SCA42, a slowly progressive ataxia, characterised by severe motor, cognitive impairment, and CA, with variable features such as facial dysmorphisms, digital anomalies, microcephaly, and epilepsy." (PMID 38003592, 2023). "Interestingly, it was shown that Cacna1g is a genetic modifier of epilepsy in a mouse model of Dravet syndrome caused by mutations in the voltage-gated Na+ channel gene Scn1a, as well as a modifier in a Scn2a mouse model of focal epilepsy." (PMID 32638069, 2020). "More recently, de novo mutations in CACNA1G were identified in some patients with childhood-onset cerebellar atrophy; clinical features were cerebellar ataxia and impaired cognitive development with other variable features, including epilepsy." (PMID 32878331, 2020). "Cacna1g has also been identified as a genetic modifier of epilepsy in the Scn1a+/− mouse model of Dravet syndrome." (PMID 37082241, 2023). "Cav3.1 is an emerging target of interest for treating intractable epilepsies, as it has been shown that genetic deletion of Cacna1g, which encodes Cav3.1, reduces spontaneous seizure frequency in a mouse model of Dravet syndrome." (PMID 36386164, 2022). "Several epilepsy modifier genes, including CACNA1G and GABRA2, were first identified in the Scn1a+/− mouse model of Dravet syndrome and later confirmed as epilepsy risk genes in humans." (PMID 34086081, 2021). "This notion is supported by previous studies showing that CACNA1G (Cav3.1) and CACNA1A (Cav2.1) are genetic modifiers of epilepsy associated with Dravet syndrome." (PMID 34399820, 2021). "The CACNA1H gene, as CACNA1G, has received much attention regarding its potential implication in inherited epilepsy phenotypes." (PMID 32638069, 2020). "CACNA1D and CACNA1G encode subunits of voltage-gated calcium channels expressed in neurons, and variants in both genes have been implicated in neurodevelopmental disorders such as autism spectrum disorder (ASD) and epilepsy." (PMID 41442065, 2025). "It has been demonstrated that transgenic alteration of Cacna1g expression acts as a modifier of epilepsy in the Scn2aQ54 mouse model of focal epilepsy, with elevated levels of Cacna1g increasing spontaneous seizure frequency, whereas reduced Cacna1g diminishing seizures." (PMID 32878331, 2020). "Three types of T-type calcium channels consisting of Cav3.1, Cav3.2, and Cav3.3 are encoded by CACNA1G, CACNA1H, and CACNA1I genes, respectively, which are expressed in the brain and play essential roles in both physiological and pathological systems, including sleep, pain, and epilepsy." (PMID 34201181, 2021). "This review delves into the significance of the CACNA genes, including CACNA1A, CACNA1B, CACNA1C, CACNA1D, CACNA1E, CACNA1G, and CACNA1H, in the pathogenesis of conditions such as migraine, epilepsy, cerebellar ataxia, dystonia, and cerebellar atrophy." (PMID 38785745, 2024). "However, so far the association of most genetic variants in CACNA1G and CACNA1H and their functional mechanism of action in terms of GOF or LOF for idiopathic genetic epilepsies is less well understood and mutations in Cav3.1 or Cav3.2 causing high risk for epilepsy have not been described." (PMID 33746731, 2021). "Involvement of both the CACNA1G and CACNA1H genes in inherited epilepsy has been proposed based on various findings in humans and mice." (PMID 33704440, 2021).
Ataxia (16 papers, 2009 to 2025). Ataxia refers to impaired coordination of voluntary muscle movement. "In conclusion, we expand the CACNA1G-associated phenotype, describing an adult patient with progressive myoclonus-ataxia and intellectual disability." (PMID 39287920, 2024). "The CACNA1G gene has been associated with various forms of cerebellar ataxia and neurological comorbidities." (PMID 32878331, 2020). "Spinocerebellar ataxia (SCA) 42 is caused by a mutation in CACNA1G, which encodes the low voltage-gated calcium channel CaV3.1 (T-type)." (PMID 33243296, 2020). "Interestingly, overexpression of the Cav3.1 channel in a Cacna1g transgenic mouse line results in a pure absence epilepsy phenotype with no ataxia or other neurological disturbances, suggesting that an increase in Cav3.1 current is sufficient to the pathogenesis of spike-wave seizures." (PMID 32638069, 2020).
absence seizures (8 papers, 2012 to 2025). "In contrast, the LOF of CACNA1G is protective against absence seizures, although the mechanistic details are unclear." (PMID 39513870, 2024). "On the other hand, transgenic murine lines overexpressing the cacna1g gene have pure absence seizures through genetic enhancement of the TC network." (PMID 24847307, 2014). "In contrast to the ameliorating effect of Cacna1g on the mouse model of Dravet syndrome, CACNA1A has a worsening effect on Dravet syndrome, meaning subjects carrying both SCN1A and CACNA1A variants develop absence seizures earlier and more frequently than patients with only SCN1A mutations." (PMID 39513870, 2024).
Cerebellar atrophy (8 papers, 2020 to 2025). Cerebellar atrophy is defined as a cerebellum with initially normal structures, in a posterior fossa with normal size, which displays enlarged fissures (interfolial spaces) in comparison to the foliae secondary to loss of tissue. "The most deleterious variants detected in the CACNA1G and CACNA1H genes, encoding Cav3.1 and Cav3.2, respectively, represent de novo gain-of-function missense mutations causing congenital severe motor and cognitive impairment with cerebellar atrophy and primary aldosteronism, respectively." (PMID 33704440, 2021).
melanoma (8 papers, 2015 to 2023). A malignant, usually aggressive tumor composed of atypical, neoplastic melanocytes. "We confirmed that human vemurafenib-adaptive melanoma cells increased expression of T-type calcium channels genes, CACNA1G and CACNA1H compared to parental cells." (PMID 32063604, 2020).
Tremor (8 papers, 2013 to 2023). An unintentional, oscillating to-and-fro muscle movement about a joint axis. "Both knockout and selective knockdown of CACNA1G have been shown to eliminate tremor in a harmaline mouse model, and TTCC blockers have shown efficacy in harmaline‐induced tremor in mice and rats in a dose‐dependent manner." (PMID 36738196, 2023).
autism spectrum disorder (7 papers, 2020 to 2025). A spectrum of developmental disorders that includes autism, and Asperger syndrome. "Also, CACNA1G was identified as a candidate gene for autism spectrum disorder (ASD) in a subset of cases but the CACNA1G association with ASD has yet to be replicated in a larger study." (PMID 32638069, 2020).
colorectal cancer (7 papers, 2007 to 2025). A primary or metastatic malignant neoplasm that affects the colon or rectum. "The expression levels of CACNA1G were also examined in diseased human GI tissues (colorectal cancer, Crohn’s disease small intestine, and diverticulitis colon)." (PMID 28806761, 2017). "The Laird methylation marker panel used to determine CIMP status of colorectal cancers consists of the CACNA1G, IGF2, NEUROG1, RUNX3 and SOCS1 genes." (PMID 20846368, 2010). "Immunohistochemical analysis (CACNA1G-N) of cross sectioned tissues showed CACNA1G protein localized in PDGFRα+/β+ cells at low level in healthy colon, but the protein was increased in PDGFRα+/β+ cells within the hypertrophied smooth muscle of colorectal cancer." (PMID 28806761, 2017). "We obtained 401 colorectal cancer specimens and successfully quantified DNA methylation in eight CIMP-specific gene promoters (CACNA1G, CDKN2A, CRABP1, IGF2, MLH1, NEUROG1, RUNX3, and SOCS1) using MethyLight technology." (PMID 31690257, 2019). "In agreement with the Western blot data, CACNA1G was increased within PDGFRα+/β+ cells and SMC in the hypertrophied smooth muscle of colorectal cancer." (PMID 28806761, 2017). "We obtained 920 colorectal cancer specimens and quantified DNA methylation in the 8 CIMP-specific gene promoters (CACNA1G, CDKN2A, CRABP1, IGF2, MLH1, NEUROG1, RUNX3 and SOCS1) by MethyLight technology." (PMID 17474983, 2007).
Dravet syndrome (7 papers, 2020 to 2024). "Inhibition of Cav3.1 has been suggested as a novel target for Dravet syndrome as knockout of Cacna1g, which encodes Cav3.1, diminished spontaneous seizures and improved survival of Scn1a+/– mice." (PMID 36386164, 2022). "Similarly, in a mouse model of Dravet syndrome due to Scn1a mutation, decreased Cacna1g expression results in a partial amelioration of disease phenotypes with improved survival and reduced spontaneous seizure frequency." (PMID 32878331, 2020). "For example, Scn1a+/− mice with decreased Cacna1g (Cav3.1) expression showed improved survival and reduced spontaneous seizure frequency, suggesting CACNA1G as a possible genetic modifier and a potential drug target for Dravet syndrome patients." (PMID 39513870, 2024). "The studies identified several genetic modifiers such as Hlf, the gene encoding hepatic leukemia factor, Cacna1g, the gene encoding Cav3.1 and Gabra2, the gene encoding the GABAA receptor α2 subunit that influence the phenotypes and severity of Scn1a+/− mouse model of Dravet syndrome." (PMID 35571373, 2022).
schizophrenia (6 papers, 2020 to 2025). A major psychotic disorder characterized by abnormalities in the perception or expression of reality. "Variants in CACNA1G, which encodes a T-type calcium channel in the thalamus, are associated with absence seizures, intellectual disabilities, and schizophrenia." (PMID 40498018, 2025). "Conversely, the loss of CACNA1G, associated with a higher risk of schizophrenia, resulted in abnormal connectivity in the thalamocortical pathway and heightened spontaneous activity in the thalamus." (PMID 40498018, 2025). "The novel interactors CACNA1I and CACNA1G targeted by nervous system drugs are calcium channels that are known to be associated with Alzheimer’s disease and schizophrenia, respectively." (PMID 32973177, 2020). "Intriguingly, transgenic expression of HERV-W ENV also led to impaired expression of several other genes that are implicated as genetic risk factors of schizophrenia and ASD, including Cacna1g, Ank3, Shank1, and Shank3." (PMID 40102613, 2025). "In addition to including members of the Set1-like H3K4 methyltransferase family (Kmt2a, Kmt2b, Kmt2c, and Kmt2d), these modules also encompassed rare variant genes associated with schizophrenia and ASD (Setd1a, Cacna1g, Ank3, Shank1, and Shank3)." (PMID 40102613, 2025).
cardiac hypertrophy (5 papers, 2017 to 2022). "Cardiac hypertrophy is associated with alterations in calcium handling and hence, it is reassuring that genes encoding for proteins involved in calcium handling and signaling (CACNA1D, CACNA1G, CACNA1S or CASC2) also show differential expression at all time points in our model." (PMID 32878883, 2020).
colon cancer (5 papers, 2011 to 2018). "In total, 31 CpG sites, located in 8 different genes (RUNX3, MLH1, NEUROG1, CDKN2A, IGF2, CRABP1, SOCS1 and CACNA1G) were investigated in 64 distinct colon cancers and 2 colon cancer cell lines." (PMID 24466191, 2014). "Highly connected biomarkers (with degree centrality) were BRAF mutation (0.19) and methylation-related markers including CDKN2A (0.17), IGF2 (0.17), RUNX3 (0.17), CACNA1G (0.15), CRABP1 (0.15), and NEUROG1 (0.15) in the proximal colon cancer network." (PMID 28623901, 2017).
gastric cancer (5 papers, 2015 to 2025). A primary or metastatic malignant neoplasm involving the stomach. "However, hypermethylation of the T-type channel gene CACNA1G (that encodes the Cav3.1 isoform) occurs in different tumors including colon, pancreatic, and gastric cancer, suggesting that it acts as a tumor suppressor." (PMID 25710007, 2015). "A total of 5 proteins, including KRT2, KRT9, DCD, EWSR1, and CACNA1G, were downregulated in gastric cancer patients in both cohorts." (PMID 38191439, 2024). "CACNA1G was associated with the most complex molecular network, which included several G-proteins and CTNNB1, a proto-oncogene that drives gastric cancer cells’ epithelial-to-mesenchymal transition." (PMID 28846697, 2017).
breast carcinoma (4 papers, 2015 to 2024). "High expression of CACNA1G was also noted in other tumor types such as colorectal, uterine, prostate, and breast cancer." (PMID 26147197, 2015). "This bioinformatics analysis revealed that different subtypes of VGCCs (CACNA1C, CACNA1D, CACNA1B, CACNA1G, and CACNA1I) are implicated in the development and progression of diverse types of cancer and show dramatic up-regulation in breast cancer." (PMID 26147197, 2015). "For instance, breast cancer showed dramatic upregulation of CACNA1C, CACNA1D, CACNA1B, CACNA1G, and CACNA1I." (PMID 26147197, 2015).
Intellectual disability (4 papers, 2020 to 2025). "Potential disease-causing variants in CACNA1G have also been identified in intellectual disability/cognitive disorders and monoallelic deletions of the CACNA1G gene have been associated with mild intellectual disability without cerebellum atrophy." (PMID 32638069, 2020).
lung carcinoma (4 papers, 2010 to 2018). "For example, clinical studies have demonstrated overexpression of CACNA1D (Cav1.3) (L type), CACNA1A (Cav2.1) (P/Q type), and CACNA1G (Cav3.1) (T type) in lung cancer, and overexpression of CACNA1A (Cav2.1) was associated with poor prognosis." (PMID 28127114, 2017). "Importantly, our study identified seven novel methylated candidates in lung cancer, including HLTF, ID4, BNIP3, H2AFX, CACNA1G, CACNA1A and TGIF." (PMID 20849603, 2010).
Alzheimer disease (3 papers, 2019 to 2020). A progressive, neurodegenerative disease characterized by loss of function and death of nerve cells in several areas of the brain leading to loss of cognitive function such as memory and language. "Perhaps a more interesting ontological category is the 11 downregulated genes associated with MAPK signaling pathway, a number of which (Arrb2, Cacna1g, Fgfr4, Taok1, Cacna1h) have been implicated in Alzheimer's disease (AD)." (PMID 33282900, 2020).
channelopathies (3 papers, 2019 to 2025). "The identification of CACNA1G in three ET families in the current study is consistent with recent reports of mutations in other ion channel genes in other ET families and the concept that the ETs are channelopathies." (PMID 31404076, 2019).